ASPM (assembly factor for spindle microtubules)
Description:
Involved in mitotic spindle regulation and coordination of mitotic processes. The function in regulating microtubule dynamics at spindle poles including spindle orientation, astral microtubule density and poleward microtubule flux seems to depend on the association with the katanin complex formed by KATNA1 and KATNB1. Enhances the microtubule lattice severing activity of KATNA1 by recruiting the katanin complex to microtubules. Can block microtubule minus-end growth and reversely this function can be enhanced by the katanin complex. May have a preferential role in regulating neurogenesis.
Synonyms: MCPH5; Calmbp1; ASP; FLJ10517; FLJ10549
Tractability: Antibody: the Human Protein Atlas places it where antibodies can reach. PROTAC: ubiquitination databases record sites on it.
Gene: Protein-coding gene on chromosome 1 (197,084,121 to 197,146,694, reverse strand). Ensembl gene ENSG00000066279.
Subcellular location: Cytoplasm; Cytoplasm, cytoskeleton, spindle; Nucleus
Subcellular location (Human Protein Atlas): Cytosol; Plasma membrane
Gene Ontology:
Molecular function: calmodulin binding
Biological process: spindle localization; spindle organization; regulation of meiotic cell cycle
Cellular component: microtubule minus-end; mitotic spindle pole; nucleus; apical plasma membrane; centrosome; cytoplasm; meiotic spindle; microtubule; midbody; spindle; spindle pole
Genetic constraint (gnomAD): Loss-of-function variants: 248 observed, 359.77 expected, observed/expected ratio (o/e) 0.69, 90% interval 0.62 to 0.77. The upper end of that interval is the gene's LOEUF score, 0.77, which puts it in group 3 of 6, group 1 being the genes least tolerant of losing a copy. Missense variants: 4,055 observed, 4,198.2 expected, observed/expected ratio (o/e) 0.97, 90% interval 0.94 to 0.99. Synonymous variants: 1,393 observed, 1,394.7 expected, observed/expected ratio (o/e) 1, 90% interval 0.95 to 1.04.
Gene-disease validity (ClinGen):
ClinGen rates the evidence that ASPM causes each of these diseases.
autosomal recessive primary microcephaly (autosomal recessive): Definitive. Autosomal recessive primary microcephaly (MCPH) is a rare genetically heterogeneous disorder of neurogenic brain development characterized by reduced head circumference at birth with no gross anomalies of brain architecture and variable degrees of intellectual impairment.
Homologues: Orthologues: chimpanzee ASPM (99% identical), macaque ASPM (96% identical), dog ASPM (80% identical), pig ASPM (69% identical), mouse Aspm (63% identical), rat Aspm (62% identical), tropical clawed frog dennd1b (45% identical), zebrafish aspm (35% identical), Drosophila melanogaster asp (15% identical). Paralogues in human: EHBP1L1 (5% identical), EHBP1 (5% identical), MICALL1 (4% identical), MICALL2 (4% identical), GAS2L1 (2% identical), SMTNL1 (2% identical), GAS2 (1% identical).
Diseases named in the same sentence as ASPM in open-access papers:
ASPM is named in the same sentence as 103 diseases in open-access papers, as found by Europe PMC text mining. Sharing a sentence is not in itself a finding about the gene and the disease. The quoted sentences say what the papers report.
microcephaly (76 papers, 2005 to 2025). A congenital or acquired developmental disorder in which the circumference of the head is smaller than normal for the person's age and sex. "Reducing overall growth produced smaller, less folded brains similar to microcephaly, which is associated with genes such as ASPM." (PMID 41459648, 2025). "This study identifies novel variants in CPAP, WDR62, and ASPM and further delineates the mutational landscape of microcephaly-associated genes in the Pakistani population." (PMID 41555927, 2025). "Mutations in the ASPM gene, causing primary microcephaly-5 (microcephaly and ID phenotypes), are the most common in our cohort (OMIM 608716)." (PMID 39281811, 2024). "Organoids generated from stem cells carrying pathogenic variants in several primary microcephaly genes, including ASPM, CDK5RAP2, CENPJ, CIT, KATNB1, and WDR62, have been shown to be smaller, consistent with the human phenotype." (PMID 39881808, 2024). "The microcephaly phenotype in AspmGt(AA0137)Wtsi-hom mice was rescued by expression of human ASPM, indicating the specific role of ASPM mutation in microcephaly." (PMID 37599996, 2023). "Retrospectively, in Europe, microcephaly in children carrying ASPM mutations was detected during pregnancy in 53% of cases, mainly during the third trimester." (PMID 37443841, 2023). "This work provides new insights to enhance our understanding of the pathogenesis of ASPM loss in diseases such as microcephaly and cancer." (PMID 37599996, 2023). "Abnormal spindle-like microcephaly-associated protein (ASPM), the human homolog of the Drosophila “spindle anomaly” gene, has been found to encode multiple transcript variants of different subtypes of microcephaly." (PMID 37335738, 2023). "In this review, we provided a comprehensive overview of the pathogenic mechanisms underlying microcephaly and cancer caused by ASPM mutations." (PMID 37599996, 2023). "Accordingly, a reduced expression of the ASPM gene in the VZ of E12 irradiated mice was described, inducing the switch from proliferative to neurogenic divisions causing microcephaly through a reduction in the number of NPCs in the VZ." (PMID 37881689, 2023). "Accordingly, differences in the phenotypic expression of available ASPM transcripts leading to different cortical surface areas have been attributed to the large phenotypic variability of primary hereditary microcephaly (MCPH) patients due to ASPM mutations." (PMID 35327983, 2022). "This indicates that other factors than ASPM expression levels are relevant for the variability of structural changes in brain morphology seen in patients with primary hereditary microcephaly caused by ASPM mutations." (PMID 35327983, 2022). "Mutations in ASPM, the most common recessive microcephaly gene, reduce the cortical volume by at least 50% in humans, but have little effect on the brains of mice, which probably reflects evolutionarily divergent functions of this protein." (PMID 35327983, 2022). "Mutations in the ASPM gene (abnormal spindle-like microcephaly-associated) are the most common cause of primary microcephaly in humans." (PMID 35883578, 2022). "The large phenotypic variability seen in patients with primary hereditary microcephaly due to ASPM mutations correlates well with the degree of structural brain abnormalities." (PMID 35327983, 2022). "The three brothers with microcephaly and mental retardation reported here carry a novel homozygous ASPM mutation, leading to a premature termination of the ASPM protein at amino acid position 1830." (PMID 35327983, 2022). "ASPM (abnormal spindle-like microcephaly-associated) gene mutations (almost exclusively nonsense, frame-shift or splice site mutations) are the most frequent underlying genetic cause for autosomal recessive MCPH." (PMID 35327983, 2022).
microcephaly (continued). "Previous studies showed that knock-down of ASPM and Wdr62, two genes implicated in microcephaly that encode mitotic spindle and centrosome proteins, also induced shortening of astral MTs in human cell lines, resulting in spindle mis-orientation." (PMID 33742057, 2021). "ASPM exerts critical roles in the symmetric divisions of neural progenitor cells of the mammalian brain, and mutations within ASPM gene are the most common cause of familial microcephaly." (PMID 34428354, 2021). "Dediu and Ladd found that populations that have a lower frequency of the derived allele of two genes that are associated with microcephaly, ASPM (rs41310927) and MCPH1 (rs930557), are more likely to speak a tone language." (PMID 32537487, 2020). "The majority of human microcephaly patients with ASPM mutations have protein truncations in or before the region encoded by exon 2613,14." (PMID 32066665, 2020). "In the present study, we identified three families having novel variants in the ASPM gene that will be helpful for geneticists and clinicians to establish reliable diagnostic strategies for primary microcephaly families in Saudi population." (PMID 33643967, 2020). "Mutations in the ASPM gene (abnormal spindle-like microcephaly-associated) are associated with microcephaly primary type 5 (MCPH5)." (PMID 30669275, 2019). "Several genes that encode for proteins implicated in centrosome function and spindle orientation are mutated in microcephaly in humans: MCPH5 or ASPM (abnormal spindle-like microcephaly associated), WDR62/MCPH2, and CEP63." (PMID 30687396, 2018). "Here, we have modeled microcephaly by generating organoids from the iPSCs of ASPM-mutation patients." (PMID 29058117, 2017). "The sequencing of ASPM gene from patient samples has revealed number of known and novel mutations associated with primary microcephaly and mental retardation." (PMID 27454254, 2016). "Abnormal Spindle-like, Microcephaly-associated (ASPM) gene is responsible for majority of the primary microcephaly patients." (PMID 27454254, 2016). "Mutations in ASPM (abnormal spindle-like microcephaly associated) are the most common cause of primary microcephaly in humans." (PMID 25729350, 2015). "We performed a combination of WES and CCCS on 27 samples (7 pedigrees), and identified a novel compound heterozygote of ASPM (RefSeqID: NM_018136.4, also known as MCPH5) mutation in one microcephaly family." (PMID 25786579, 2015). "By examining the entire exome, in particular the many genes known to be associated with microcephaly, led to the finding of mutations in ASPM." (PMID 25735936, 2015). "Mutations in the MCPH1 (Microcephalin) and ASPM (abnormal spindle-like microcephaly associated) genes cause primary microcephaly." (PMID 24830737, 2014). "The results of our phylogenetic comparative analyses provide direct evidence that evolution of brain size is indeed linked to four microcephaly genes (ASPM, CDKRAP2, STIL, WDR62) in two mammalian clades, Glires and Euungulata." (PMID 24898820, 2014). "In ASPM mutant mice, truncated ASPM proteins similar to those that cause microcephaly in humans fail to localize to the midbody during M phase." (PMID 23152892, 2012). "The human ASPM product has been linked to this function, because mutations in its coding region lead to severe microcephaly." (PMID 21559369, 2011). "In particular, ASPM is involved in the control of neuronal progenitor proliferation and is associated with microcephaly." (PMID 20498707, 2010). "ASPM regulates brain growth and mutations in this gene were shown to be associated with microcephaly." (PMID 18541031, 2008). "Several other microcephaly-associated genes such as ASPM and microcephalin experienced recent adaptive evolution apparently linked to brain size expansion in humans." (PMID 16749933, 2006).
microcephaly (continued). "The authors examined a locus (Cernunnos-XLF) associated with microcephaly because of the evidence that other genes linked to this disorder have evolved under adaptive evolution in humans (ASPM and microcephalin)." (PMID 16749933, 2006). "In 2002, mutations in the genes ASPM (abnormal spindle-like microcephaly associated) and microcephalin were identified as two causes of microcephaly." (PMID 15760271, 2005). "However, elucidating the mechanisms underlying the cooperation of ASPM with these factors in microcephaly and other diseases will require further investigation." (PMID 37599996, 2023). "Moreover, modeling ASPM mutations demonstrated the ability of human COs to recapitulate microcephaly." (PMID 36340790, 2022). "Mutations in microcephaly genes like assembly factor for spindle microtubules (ASPM), CDK5 regulatory subunit associated protein 2 (CDK5RAP2), microcephalin 1 (MCPH1), and centromere protein J (CENPJ) underwent pervasive positive selection during human evolution." (PMID 36550402, 2022). "This study, thus, further endorses ASPM mutations as the most frequent cause of microcephaly." (PMID 34295862, 2021). "ASPM plays an important role in controlling the neurogenesis and cerebral cortical size, and its homozygous mutation can lead to apoptosis of neural progenitor cells and microcephaly." (PMID 32667745, 2020). "In addition, PAK2/Pak within 3q29, TBX1/org-1 within 22q11.2, autism-associated CHD8/kis, and microcephaly-associated ASPM/asp also showed smaller wing areas and vein lengths." (PMID 32579612, 2020). "Many of the ASPM mutations causing primary microcephaly have been reported so far." (PMID 33643967, 2020). "Another gene connected with the brain size regulation, ASPM (abnormal spindle-like microcephaly associated, MCPH5), also evolved faster in hominids than in the other primates, having the highest rate of non-synonymous to synonymous substitutions in the human lineage." (PMID 32912141, 2020). "However, human NDE1-associated microcephaly is much more severe than the forms of the disorder involving mitotic spindle assembly genes, such as ASPM and WDR62 (refs 4, 5)." (PMID 27553190, 2016). "In particular, ASPM (abnormal spindle-like microcephaly-associated) has been a focus of speculation with respect to the dramatic evolution of brain size in humans." (PMID 20573239, 2010). "In this regard, it is conceivable that one or more of the human-specific NR2E1 sites identified in the present study may have been fixed by positive selection in a manner similar to that proposed for ASPM, which is mutated in some patients with microcephaly." (PMID 17054721, 2007). "In conclusion, we found three novel mutations in the ASPM gene in Saudi families that will help to establish a disease database for specified mutations in Saudi population and will further help to identify strategies to tackle primary microcephaly in the kingdom." (PMID 33643967, 2020). "In addition to microcephaly-related genes that have been implicated in previous studies [especially ASPM (rs41310927)], we also examined a number of genes that have been hypothesized to be related to general cognitive and language processing." (PMID 32537487, 2020). "Although ASPM was part of a signature of 254 genes predictive of metastasis, a functional role for this gene in metastatic progression is not obvious given its known role as a spindle protein that regulates brain size with mutations in the gene being associated with microcephaly." (PMID 20520718, 2010). "In this study, we investigated four consanguineous families with congenital microcephaly and identified three novel variants in CPAP, WDR62, and ASPM." (PMID 41555927, 2025).
microcephaly (continued). "This trajectory of early postnatal brain growth restriction has also been reported in individuals affected by paradigmatic primary microcephaly genes such as ASPM." (PMID 40210435, 2025). "For example, several genes associated with mitotic spindle formation and cell division—such as ASPM and CENPJ—have been linked to microcephaly, which is thought to be due to defects in neurogenesis." (PMID 39881808, 2024). "All common mutations causing microcephaly are present in genes implicated in cell division (MCPH1, ASPM, CDK5RAP2, CENPJ, STIL, WDR62, and CEP152)." (PMID 37294214, 2023). "Biallelic mutations in ASPM (MCPH5 MIM #605481) occur more frequently than other genes in MCPH, underlying up to 40% of all the reported primary microcephaly cases." (PMID 34295862, 2021). "ASPM knockdown in animal models leads to a decrease in cortical area and microcephaly as observed in humans." (PMID 34295862, 2021). "ASPM (abnormal spindle‐like microcephaly) gene, also known as MCPH5, is the most common family microcephaly mutation gene involved in the regulation of neurogenesis and cerebral cortical size." (PMID 32667745, 2020). "ASPM plays a role in the pathoaetiology of microcephaly with potential involvement in other NDDs3,5." (PMID 32066665, 2020). "Whole exome sequencing of the patient identified a novel homozygous frameshift mutation (c.2738dupT, p.Cys914fs) in exon 9 Abnormal Spindle-like Microcephaly (ASPM) gene." (PMID 31970108, 2019). "A number of microcephaly genes have been identified, including ASPM, microcephalin/BRIT1, CDK5RAP2/Cep215, CENPJ/CPAP, SIL/STIL, WDR62, and NDE1 (refs 3, 4, 5)." (PMID 27553190, 2016). "Microcephaly is also a reported, plausibly due to the functional link between TBR1 and ASPM, a robust candidate for microcephaly, and candidate for positive selection in human lineage." (PMID 26136701, 2015). "Using phylogenetically corrected comparative analyses, we find that the evolution of two microcephaly loci, ASPM and CDK5RAP2, are correlated with neonatal brain size in Glires and Euungulata, the two most densely sampled non-primate clades." (PMID 24898820, 2014). "Much of the early focus on the molecular evolution of microcephaly genes centered on the role of two loci (ASPM and MCPH1) in human evolution." (PMID 24898820, 2014). "To summarize, the data presented here showed that the Angelman syndrome protein UBE3A interacts with primary microcephaly protein ASPM and, like ASPM and other MCPH proteins, localizes to centrosomes." (PMID 21633703, 2011). "The data also indicate that ASPM mutations are restricted to individuals with an MCPH phenotype, and suggest ASPM testing in primary microcephaly is clinically of use." (PMID 19028728, 2009). "Numerous mutations in the ASPM gene have been identified in MCPH patients, some of which have been incorporated into different animal models seeking to investigate the pathological mechanisms of ASPM mutation in microcephaly." (PMID 37599996, 2023). "Mouse models have been widely used to study the function of ASPM, and research has revealed that ASPM mutations are found not only in microcephaly but also in other diseases and disorders." (PMID 37599996, 2023). "ASPM has many roles explaining its involvement in the process of microcephaly." (PMID 37427375, 2023). "However, further research is needed to enhance our understanding of the role of ASPM-related DNA repair in neurological disorders such as microcephaly." (PMID 37599996, 2023). "Loss of PV+ interneurons in Aspm1–7 mice may also relate to the observed ventriculomegaly and corpus callosum dysgenesis that resemble alterations seen in human microcephaly patients with ASPM mutations and in Aspm−/− mice." (PMID 32066665, 2020). "To determine whether estradiol could regulate the seven currently known microcephaly genes (ASPM, CENPJ, CEP152, CDK5RAP2, MCPH1, STIL and WDR62), we conducted a search of the potential ERE (estrogen response element) sites in gene promoter regions." (PMID 26123139, 2015).